RNU1-24P (RNA, U1 small nuclear 24, pseudogene)
Synonyms: U1.41
Gene: Small nuclear RNA gene on chromosome 13 (101,778,884 to 101,779,048, reverse strand). Ensembl gene ENSG00000201155.
Homologues: Orthologues: chimpanzee U1 (98% identical), macaque U1 (93% identical), pig U1 (76% identical), dog U1 (72% identical), mouse Gm23727 (72% identical), dog U1 (68% identical), mouse Gm24145 (68% identical), rat LOC120102668 (68% identical), rat U1 (65% identical), mouse Gm23039 (65% identical), mouse Gm24291 (64% identical), rat U1 (62% identical), and 2 more. Paralogues in human: RNU1-1 (81% identical), RNU1-2 (81% identical), RNU1-27P (81% identical), RNU1-28P (81% identical), RNU1-3 (81% identical), RNU1-4 (81% identical), RNVU1-18 (81% identical), RNVU1-28 (81% identical), RNVU1-29 (81% identical), U1 (81% identical), RNU1-138P (80% identical), RNU1-78P (80% identical), and 134 more.